GPI (glucose-6-phosphate isomerase)
Diseases named in the same sentence as GPI in open-access papers (continued):
Sharing a sentence is not in itself a finding about the gene and the disease.
Parkinson disease (16 papers, 2013 to 2025). A progressive degenerative disorder of the central nervous system characterized by loss of dopamine producing neurons in the substantia nigra and the presence of Lewy bodies in the substantia nigra and locus coeruleus. "Nonetheless, parkinsonism was associated with three principal abnormalities in perimovement activity: 1) The timing of GPi responses became uncoupled from movement onset with respect to both mean latency and trial-to-trial variability in timing." (PMID 39257740, 2025). "The results so far suggest that parkinsonism was associated with changes in the timing and shape of perimovement modulations in GPi activity." (PMID 39257740, 2025). "Several network models evaluated the effect of dopamine on GPi (primate analog of EP) oscillatory firing, to investigate mechanisms underlying Parkinson's beta oscillations and normalization by DBS." (PMID 33815062, 2021). "For example, if it is observed that every case of increased GPi neuronal activity is consistently associated with Parkinsonism, then one can induce that all cases of Parkinsonism are due to overactivity of the GPi neurons." (PMID 27708569, 2016). "For example, the increased responsiveness of GPi neurons to active movement fits with the general idea that parkinsonism is associated with a breakdown in the functional segregation between circuits throughout the BG (i.e., reduced neuronal selectivity for specific sensory stimuli)." (PMID 39257740, 2025). "One recent study revealed that the GPi itself could be the region underlying stimulation-induced Parkinsonism." (PMID 34912201, 2021). "In Parkinson's disease (and experimentally created low-dopamine states), hypokinetic symptoms are associated with an increase of synchronized oscillatory activity in the β frequency band (10–30 Hz, broadly speaking) in basal ganglia-thalamocortical circuits including GPi." (PMID 24046745, 2013). "Here, by measuring mean firing rates during the periods of attentive rest defined by the task’s start position hold intervals, we compared GPi activity during the same relatively well-controlled behavioral state before and after the induction of parkinsonism." (PMID 39257740, 2025). "According to this model, the slowing of movement seen in parkinsonism can be attributed to an attenuation of task-related decreases in GPi firing and their disinhibitory effect on downstream motor circuits." (PMID 39257740, 2025). "For both neural correlates, the change induced by parkinsonism was consistent with a breakdown in the temporal coupling of GPi responses to movement onset." (PMID 39257740, 2025). "To summarize, the normally strong temporal linkage of many GPi responses to movement initiation was reduced following the induction of parkinsonism." (PMID 39257740, 2025). "Perimovement changes in GPi activity were diminished in size and prolonged in duration following the induction of parkinsonism." (PMID 39257740, 2025). "Since globus pallidus pars interna (GPi) is now known to be a target for dystonia and Parkinson’s disease (PD), current research has concentrated on figuring out how GPi-DBS affects motor networks." (PMID 39336425, 2024). "This phenomenon appears different than GPi induced parkinsonism, however, comparative studies should be performed to observe if parkinsonism involves a common network pathway." (PMID 33240065, 2020). "GPi neurons tend to fire in a synchronized manner due to Parkinson's disease while DBS waveforms have a desynchronization effect on these firing patterns." (PMID 28848417, 2017). "In contrast, when the spikes in the GPi triggered the system, parkinsonism worsened, together with increased GPi oscillatory activity." (PMID 26979514, 2016). "For example, if overactivity of the GPi neurons (or increased beta-oscillations or increased synchrony) implies Parkinsonism and Parkinsonism is found, then there must be GPi neuronal overactivity (or increased beta-oscillations or increased synchrony)." (PMID 27708569, 2016).
Parkinson disease (continued). "The differential attenuation of decrease-type responses is consistent with the concept that decrease-type GPi responses are pro-kinetic and that their attenuation may play a role in the pathophysiology of parkinsonism." (PMID 39257740, 2025). "In addition, we found that the normally-common trial-to-trial linkage of GPi responses to movement onset was markedly reduced following the induction of parkinsonism." (PMID 39257740, 2025). "GPi activity during those two distinct behavioral states may be affected differently by the induction of parkinsonism." (PMID 39257740, 2025). "For example, stimulation of subthalamic nucleus (STN) or internal globus pallidus (GPi) in Parkinson's disease can have immediate effects on bradykinesia, whereas stimulation of GPi in either genetic or acquired dystonias usually has effects only weeks or months later." (PMID 30294268, 2018). "By contrast, ablation of the GPi has been shown to improve the conditions of patients suffering from Parkinson’s disease, which suggests that abnormal information processing in the GPi may have a greater influence on motor behavior than its silencing." (PMID 24574980, 2014). "The somewhat unexpected effect on mean firing rates found here may be related to the fact that our animals were engaged in a learned behavioral task combined with the possibility that the effects of parkinsonism on mean GPi firing rates differ between behavioral states." (PMID 39257740, 2025). "First, nearly all past studies examined the effects of parkinsonism on GPi activity in animals that were not engaged in a defined behavioral task." (PMID 39257740, 2025). "Recordings from nonhuman primates and Parkinson’s disease are consistent with the hypothesis of high GPi activity at rest; therefore, the GPi output orthodromic pathway (to thalamus) is reduced by the BDZ, as the results show." (PMID 37638186, 2023).
Dyskinesia (12 papers, 2012 to 2025). A movement disorder which consists of effects including diminished voluntary movements and the presence of involuntary movements. "The GPi is the primary target for generalized dystonia, an alternative target for PD—particularly when associated with severe dyskinesia or mild cognitive impairment, and a possible target for Tourette syndrome." (PMID 34367055, 2021). "Therefore, the observed plasmalogen deficiency in the GPi and associated PrG region, where the primary motor cortex resides, supports a link between dyskinesia-induced plasmalogen depletion and dysfunction in these motor circuits." (PMID 40849420, 2025). "One of the studies showed high mortality with other targets, while GPi was selected as the best target for severe dyskinesia." (PMID 37492334, 2023). "Nevertheless, our data suggest that GPi stimulation can effectively ameliorated motor complications in younger onset PD patients, especially on dyskinesia." (PMID 36207312, 2022). "For example, GPi stimulation effects are site-specific such that the stimulation of the ventral GP improves levodopa-induced dyskinesia, while dorsal stimulation can induce dyskinesia." (PMID 34367055, 2021). "The metabolic activity reduction and firing reduction and firing frequency changes in firing pattern of GPi activity to the thalamus are thought to produce an increase in thalamocortical drive leading to dyskinesia." (PMID 23125942, 2012). "Targeting GPi seems to have a particular advantage in treating dyskinesia." (PMID 39628904, 2024). "On the other hand, GPi has been shown to be particularly effective at reducing dyskinesia symptoms and activities of daily living within the first 5 years of treatment, and it may offer a means of improving the quality of life of the patient shortly after initiating DBS." (PMID 39628904, 2024). "Since GPi directly suppresses dyskinesias, it may serve to affect the contralateral side as well and continue to exert effects even without medication reductions, which makes unilateral GPi an attractive option for patients with severe one-sided dyskinesias." (PMID 28706748, 2017). "Fortunately, the main goal of the treatment was reduction of the disabling orofacial peak‐dose dyskinesia, therefore, targeting the GPi was considered appropriate irrespective of the technique applied, DBS, or MRgHiFUS." (PMID 35844284, 2022). "In addition, STN and GPi activity was decreased when assessed by regional brain uptake of 2-deoxyglucose, which measures afferent synaptic activity, in MPTP monkeys with dyskinesias induced by dopaminergic drugs." (PMID 23125942, 2012). "Indeed, injection of dopamine agonists in MPTP treated nonhuman primates induced dyskinesia and showed a marked decrease in GPi firing rates." (PMID 25910230, 2015).
endometrial cancer (12 papers, 1978 to 2025). Primary or metastatic malignant neoplasm involving the endometrium (mucous membrane that lines the endometrial cavity). "In agreement with our results, some studies also showed that increased expression levels of GPI were associated with poor prognosis in patients with clear cell-renal cell carcinoma, lung carcinomas, endometrial carcinoma, and BRCA." (PMID 36246907, 2022). "GPI, GPT, and LPCAT1 were frequently overamplified in endometrial cancer patients, while ADCY9 more often had missense mutations (unknown significance)." (PMID 32894095, 2020).
rheumatoid arthritis (10 papers, 2005 to 2025). A chronic, systemic autoimmune disorder characterized by inflammation in the synovial membranes and articular surfaces. "GPI is an important autoantigen in human rheumatoid arthritis (RA), and GPI levels, including soluble GPI and GPI immune complexes, are significantly increased in serum and synovial fluid in RA patients." (PMID 34912709, 2021). "The autoantibodies associated with rheumatoid arthritis (RA) predominantly consist of RF, ACPA, anti-modified citrullinated vimentin antibody, anti-carbamylated protein antibody, anti-PAD-4 antibody, and anti-GPI antibody." (PMID 39049070, 2024). "Experimental rheumatoid arthritis (RA) was induced by intraperitoneal injection of glucose-6-phosphate-isomerase-specific antibodies (GPI) containing serum." (PMID 32514887, 2020). "The higher level of Glucose-6-phosphate isomerase (G6PI) has been found in both synovial tissue and synovial fluid of rheumatoid arthritis (RA) patients, while the function of G6PI in RA remains unclear." (PMID 28067317, 2017). "Furthermore, the synovium of patients with rheumatoid arthritis both with and without anti-glucose-6-phosphate isomerase antibodies showed frequent IGVH4-31 gene usage." (PMID 36826743, 2023).
melanoma (8 papers, 2017 to 2024). A malignant, usually aggressive tumor composed of atypical, neoplastic melanocytes. "Knockdown of glucose-6-phosphate isomerase caused glycolytic inhibition in colon cancer and melanoma cells while elevating the level of oxidative phosphorylation, which investigators consider to be a compensatory response of cells to glycolytic inhibition." (PMID 36900384, 2023). "In this study, six genes (ADCYAP1R1, GPI, IFITM1, KIR2DL4, LIF, and NTS) were identified as being closely associated with prognosis among a pool of 1793 melanoma-related genes." (PMID 38217549, 2024). "Six genes closely associated with the prognosis of melanoma patients, including ADCYAP1R1, GPI, IFITM1, KIR2DL4, LIF and NTS, were elected to fabricate a prognosis model." (PMID 38217549, 2024). "In conclusion, we reported the association of HRGs with patient prognosis in melanoma and screened for novel gene signatures, including FBP1, NDRG1, GPI, IER3, B4GALNT2, BGN, PKP1, and EDN2." (PMID 37422626, 2023). "In this study, six genes (ADCYAP1R1, GPI, IFITM1, KIR2DL4, LIF, and NTS) that exhibited strong correlation with the prognosis of melanoma patients were identified." (PMID 38217549, 2024). "Baicalein and baicalin treatments markedly suppressed gene expression of Glut1, Glut3, HK2, TPI, GPI, and PFK1 in both human and mouse melanoma cells." (PMID 32984331, 2020). "Our findings indicate that ADCYAP1R1, GPI, and NTS may contribute to a poor prognosis in melanoma patients, while IFITM1, KIR2DL4, and LIF are more likely to be associated with a better prognosis in individuals with melanoma." (PMID 38217549, 2024).
lung adenocarcinoma (7 papers, 2021 to 2024). A carcinoma that arises from the lung and is characterized by the presence of malignant glandular epithelial cells. "The novelty of the study lies in the identification of GPI (glucose-6-phosphate isomerase), a plasma protein, as a diagnostic and prognostic marker in lung adenocarcinoma (LUAD)." (PMID 38573114, 2024). "The Glucose-6-phosphate isomerase (GPI) gene plays an important role in glycolysis and gluconeogenesis and has been identified as a biomarker for lung adenocarcinoma." (PMID 37915799, 2023). "The expression of the 6 key genes (FKBP3, GPI, LOXL2, IL22RA1, GPR37, has-miR-148a-3p) in lung adenocarcinoma patients with different tumor stages, T stages, N stages and M stages." (PMID 34040139, 2021). "Correlation between glucose-6-phosphate isomerase (GPI) expression and the clinicopathological features of the lung adenocarcinoma (LUAD) cases from The Cancer Genome Atlas (TCGA)." (PMID 34912709, 2021).
lung carcinoma (7 papers, 1988 to 2023). "The results showed that, compared with that in normal tissues, GPI expression was significantly higher in tumor tissues such as bladder cancer, colorectal cancer, gastric cancer, kidney cancer, lung cancer, ovarian cancer, and lymphoma." (PMID 34912709, 2021). "Six genes (PGK1, ENO2, GPI, PEKP, ALDOA, and ANGPTL4) were reported as hypoxia-related genes in lung cancer." (PMID 38248716, 2023).
ovarian carcinoma (7 papers, 2017 to 2023). A malignant neoplasm originating from the surface ovarian epithelium. "The expression of MTF1 and BMP6 involved in iron regulation was associated with improved OS in ovarian cancer, whereas the expression of IREB2, GPI, and HMOX1 in this process was associated with poor OS in ovarian cancer." (PMID 38186569, 2023). "Kaplan-Meier plotter analysis indicated that among the highly expressed glycolysis genes, SLC16A3, HK2, GPI, PFKP, and PGK1, were closely associated with poor PFS, PPS, or OS in patients with ovarian cancer." (PMID 34277429, 2021). "In ovarian cancer, the lncRNA NRCP interacts with STAT1 and RNA polymerase II, leading to increased expression of glucose-6-phosphate isomerase and modulation of glycolysis." (PMID 29371936, 2017). "The silencing of lncRNA-NRCP could reduce the levels of glucose-6-phosphate isomerase ALDOA and ALDOC. lncRNA-NRCP via STAT1 could promote glycolysis in ovarian cancer cells." (PMID 33123468, 2020).
Obesity (5 papers, 2015 to 2023). Accumulation of substantial excess body fat. "These enzymes were glucose 6-phosphate isomerase (GPI), triosephosphate isomerase (TPI), enolase (Eno3), lactate dehydrogenase (LDHa), glyoxalase-1 (Glo1) and the mitochondrial DLD, whose expressions were modified by AM251 in hypercaloric diet-induced obesity." (PMID 26671069, 2015).
autoimmune disease (4 papers, 2016 to 2022). A disorder resulting from loss of function or tissue destruction of an organ or multiple organs, arising from humoral or cellular immune responses of the individual to their own tissue constituents. "Although both GPI and anti-GPI have been detected in the sera of patients with autoimmune diseases, serum GPI has been proposed to be a valid biomarker which is more specific to autoimmune diseases than anti-GPI." (PMID 28384257, 2017).
colon carcinoma (4 papers, 2016 to 2023). "Furthermore, five of the seven glycolytic and PPP enzymes identified in our interactome analysis (GOT2, GPI, PGD, PSAT1, and TKT) were found to map to the “Metabolic reprogramming in colon cancer” pathway." (PMID 30108113, 2018). "However, [18F]FLT is able to detect inflammation in arthritic ankles of glucose-6-phosphate-isomerase (GPI) serum-injected mice and proliferation of carcinoma cells in subcutaneous CT26 mouse colon tumors." (PMID 27701464, 2016).
COVID-19 (4 papers, 2021 to 2024). A disease caused by infection with severe acute respiratory syndrome coronavirus 2. "Clustering and shared upregulation of glycolytic enzyme encoding genes GALM, GAPDH, GPI, and ALDOA together with HIF1A, and transcripts regulating exhaustion (TIGIT and LAG3) suggested that hypoxia/anaerobic axis is associated with impaired CD8+TM function in COVID-19 BALF." (PMID 37029220, 2023).
osteosarcoma (4 papers, 2014 to 2024). A usually aggressive malignant bone-forming mesenchymal neoplasm, predominantly affecting adolescents and young adults. "We constructed an HBP-related gene signature containing five key genes (GPI, PGM3, UAP1, OGT, MGEA5) which showed a remarkable prognostic value for predicting prognosis and can guide immunotherapy and targeted therapy for osteosarcoma." (PMID 36275679, 2022).
Tremor (4 papers, 2018 to 2023). An unintentional, oscillating to-and-fro muscle movement about a joint axis. "Hutchison and colleagues clearly demonstrated a linear relationship between the peak frequency of limb tremor and GPi tremor frequency activity suggesting that GPi is involved in the genesis of rest tremor." (PMID 30065816, 2018). "There is increasing evidence to support the role of GPi in the pathogenesis of tremor." (PMID 33192410, 2020).
anemia (3 papers, 2019 to 2024). A reduction in the number of red blood cells, the amount of hemoglobin, and/or the volume of packed red blood cells. "The essential enzyme glucose-6-phosphate isomerase (GPI) is an example of a moonlighting protein that has been linked to anemia and neurological pathologies due to its multifuncional nature." (PMID 32587857, 2020).
clear cell renal cell carcinoma (3 papers, 2015 to 2022). "In this study, we assessed the role of GPI/AMF as a prognostic factor for clear cell renal cell carcinoma (ccRCC) cancer-specific (CSS) and progression-free survival (PFS)." (PMID 26579829, 2015). "In addition to Ndufa4l2, we performed immunoblotting of α-Enolase 1 (Eno1), a prognostic marker in clear cell renal cell carcinoma, and glucose-6-phosphate isomerase (Gpi1), independent adverse prognostic markers of ccRCC aggressiveness and progression-free survival." (PMID 34970493, 2021).
colorectal cancer (3 papers, 2008 to 2024). A primary or metastatic malignant neoplasm that affects the colon or rectum. "Moreover, the abundance of glycolysis enzymes (GPI, LDHA) in CHMp exosome was verified with Western blotting, To broaden the scope, we extended to human colorectal cancer-derived exosomes (SW480 vs. SW620) for comparison." (PMID 38419074, 2024).
gastric cancer (3 papers, 2021 to 2022). A primary or metastatic malignant neoplasm involving the stomach. "According to one study, GPI mRNA expression is a promising biomarker for the prognosis of gastric cancer (GC)." (PMID 36276846, 2022).
liver cancer (3 papers, 2023 to 2024). An epithelial or non-epithelial malignant neoplasm that arises from the liver. "Oleuropein, an iridoid ether terpene glycoside found in plants, targets glucose-6-phosphate isomerase (GPI) to inhibit glycolysis and tumor growth in liver cancer." (PMID 39609317, 2024). "Esculetin (at a concentration of 50 mM) was effective against HepG2 liver cancer cells, by binding to three potential targets (phosphoglycerate kinase 2 (PGK2), glycerol-3-phosphate dehydrogenase (GPD2) and glucose-6-phosphate isomerase (GPI))." (PMID 37175299, 2023).